SLC26A4 (solute carrier family 26 member 4)
Diseases named in the same sentence as SLC26A4 in open-access papers (continued):
Sharing a sentence is not in itself a finding about the gene and the disease.
hearing loss (continued). "The aim of this study was to examine the SLC26A4 mutation spectrum and prevalence among congenital hypothyroidism (CH) patients in the Guangxi Zhuang Autonomous Region of China and to establish how frequently PS causes hearing impairment in our patients with CH." (PMID 26886089, 2016). "The SLC26A4 gene (solute carrier family 26, member 4, 7q22.3, OMIM #605646, NCBI: NM_000441.2) is one of the key genes involved in the etiology of hearing loss." (PMID 41226768, 2025). "We have recruited a cohort of 32 Austrian patients with hearing loss and EVA to define the prevalence and type of pathogenic sequence alterations in SLC26A4 and discover novel EVA-associated genes." (PMID 40121402, 2025). "Thirty‐three children had bilateral hearing loss (GJB2 = 25, SLC26A4 = 8) and two children had unilateral hearing loss (GJB2 = 2, SLC26A4 = 0) at the time of genetic testing." (PMID 40008839, 2025). "The aim of the study was to determine the genetic etiology of hearing loss with EVA or with fully developed PDS in 37 probands and the functional characterization of novel variants identified in the SLC26A4 gene." (PMID 40426046, 2025). "The genetic variants of GJB2, SLC26A4, LMX1A are involved in inner ear development and associated with the occurrence of asymmetric sensorineural hearing loss." (PMID 39373914, 2025). "Before conducting genetic testing on patients with hearing loss, we performed a prescreening for pathogenic variants in GJB2 and SLC26A4, the two most prevalent causative genes for nonsyndromic hearing loss in Korean individuals." (PMID 40164689, 2025). "Pendred syndrome/DFNB4 is the third most common genetic cause of hearing loss, with SLC26A4 mutations accounting for 6% of hereditary hearing loss cases." (PMID 39932986, 2025). "Newborn audiological screening identified hearing loss in 20/35 (57%) of children in this cohort (14/27 52% GJB2‐HL; 6/8 75% SLC26A4‐HL) and all 20 children were referred based on findings in both ears." (PMID 40008839, 2025). "Patients with genetic variants of GJB2, SLC26A4, and LMX1A showed significantly higher detection of EH compared to other causes of hearing loss." (PMID 39373914, 2025). "There are several papers reporting NGS analysis results for hearing loss patients; however, many of them pre-screened GJB2- or SLC26A4-associated HL cases, making it difficult to estimate the true prevalence of MYO7A-associated HL." (PMID 38594301, 2024). "Other studies also indicated that, apart from GJB2, pathogenic variants in SLC26A4, MYO15A, OTOF, and CDH23 are a frequent cause of hearing loss in European populations (Hilgert, Smith, Van Camp, 2009)." (PMID 39498320, 2024). "Enlarged vestibular aqueduct (EVA) is a frequently occurring inner ear malformation that associates with sensorineural hearing loss (SNHL), with SLC26A4 being the responsible gene." (PMID 40225947, 2024). "To investigate the association between hereditary hearing loss and vestibular function, we compared vestibular function and symptoms among patients with GJB2, SLC26A4, and CDH23 variants." (PMID 38720048, 2024). "The major genetic causes of integral hearing loss are GJB2 and SLC26A4, while specific AN is totally different." (PMID 38456936, 2024). "Pathogenic variants in the SLC26A4 gene (solute carrier family 26, member 4/pendrin, 7q22.3, OMIM 605646) are one of the most common causes of hearing loss worldwide." (PMID 37107686, 2023). "Over 5% of the world population has hearing loss problems (according to WHO data) and among these 3–5% is attributed to SLC26A4 disease-associated mutations varying by ethnicity." (PMID 37230976, 2023). "Pathogenic variants in the SLC26A4, FOXI1, and KCNJ10 genes are associated with hearing loss (HL) and specific inner ear abnormalities (DFNB4)." (PMID 36499699, 2022). "This is because there are hotspot genes and variants in the Chinese hearing loss population, such as GJB2 c.235del, SLC26A4 c.919-2A>G, and MT-RNR1 m.1555A>G." (PMID 36568381, 2022).
hearing loss (continued). "Molecular epidemiological studies in China have identified several common deafness genes, such as GJB2, SLC26A4, and MT-RNR1, which account for 30%–50% of congenital hearing loss cases." (PMID 36568381, 2022). "However, whether these mutations in SLC26A4 are related to hearing loss remains unknown." (PMID 36072472, 2022). "Our findings expand the gene mutation spectrum of SLC26A4 and provide additional knowledge for diagnosis and genetic counseling associated with EVA-induced hearing loss." (PMID 35804348, 2022). "Of the 52 patients with hearing loss, genetic factors were identified for 39 patients (75.0%); GJB2 and SLC26A4 were the most common genes identified." (PMID 35816303, 2022). "CDH23-associated hearing loss, along with SLC26A4, is the second or third most frequent type of hearing loss after GJB2-associated hearing loss." (PMID 35020051, 2022). "Although SLC26A4 variants that cause hearing loss have AR inheritance, a number of previous studies demonstrated EVA with monoallelic SLC26A4 variants." (PMID 34593925, 2021). "The hearing loss in four other patients was caused by pathogenic biallelic variants in the well-known hearing loss-causing genes: STRC (OMIM 606440); MYO15A (OMIM 602666); SLC26A4 (OMIM 605646); and LOXHD1 (OMIM 613072)." (PMID 34062854, 2021). "Among these hearing loss genes, GJB2 and SLC26A4 gene variants were most common in Chinese deaf population." (PMID 34335733, 2021). "Medians of ABR thresholds were 10-20 dB higher in injected compared to Slc26a4+/+ mice, which is consistent with a mild hearing impairment." (PMID 31695761, 2019). "Although many new genes have been found, the most common genes associated with hearing impairment still are GJB2, SLC26A4, and mtDNA 12S rRNA." (PMID 30693673, 2019). "Among the hereditary hearing loss, the c.235delC in GJB2 gene was identified as the most frequent pathogenic variant, followed by p.H723R in SLC26A4 in Japanese population." (PMID 31645975, 2019). "In Caucasian cohorts, approximately 50% of all individuals with unilateral or bilateral hearing loss and EVA carry at least one mutant SLC26A4 allele." (PMID 29320412, 2018). "In particular, GJB2, SLC26A4, MYO15A, OTOF, and CDH23 are the most common genes responsible for hereditary hearing loss." (PMID 30068307, 2018). "Among 88 cochlear implantees with autosomal recessive non-syndromic hearing loss, subjects with GJB2 and SLC26A4 mutations were excluded." (PMID 29072634, 2017). "We developed a PCR-reverse dot blot (RDB) assay for screening 20 hotspot mutations of GJB2, GJB3, SLC26A4, and MT-RNR1, which are common non-syndromic hearing loss (NSHL)–associated genes in the Chinese population." (PMID 28505178, 2017). "The GJB2, SLC26A4, MT-RNR1 and MT-TS1 genes have been reported as major pathogenic genes in nonsyndromic hearing loss." (PMID 28225033, 2017). "With the exception of SLC26A4 and GJB2 mutations, mutations in genes linked to hearing loss are extremely rare and can be effectively evaluated by WES31." (PMID 28383030, 2017). "Mutations in the SLC26A4 gene are the second most frequent cause of human hereditary HL, after mutations in the GJB2 gene, accounting for ~ 10% of all hereditary hearing impairment cases." (PMID 27082237, 2016). "Mutations in various hearing loss-related genes have been studied worldwide, and severalgenes have been identified as commonly related to hearing impairment, such asGJB2, SLC26A4, GJB3 andMT-RNR1 (mtDNA 12S rRNA gene)." (PMID 27727359, 2016). "Regarding the onset of hearing loss, mutations in GJB2 and SLC26A4 were principally found in the early-onset group." (PMID 27627659, 2016). "In thisstudy, we analyze nine common gene mutations (GJB2,SLC26A4, GJB3 and MT-RNR1) in 738children with severe or profound hearing loss in Inner Mongolia." (PMID 27727359, 2016).
hearing loss (continued). "In this study, the relative genetic contribution of the CDH23 mutation to nonsyndromic arSNHL was estimated in a Korean pediatric hearing loss cohort, and the genetic load of GJB2 and SLC26A4 was documented." (PMID 26264712, 2015). "The gene most commonly involved in hearing loss worldwide is GJB2, while SLC26A4 is also frequently involved in congenital hearing impairment." (PMID 24767429, 2014). "Mutations in the SLC26A4 (PDS, GeneID: 5172) gene are the second most frequent cause of human hereditary hearing impairment worldwide, next to mutations in the GJB2 (GeneID: 2706) gene." (PMID 23755160, 2014). "Malfunction of the SLC26A4 protein can cause NSEVA and Pendred syndrome (PS), a type of syndromic sensorineural hearing loss characterized by EVA, goiter, and in some cases Mondini malformation." (PMID 25372295, 2014). "Genetic analysis revealed that among the etiology of non-syndromic hearing impairment, GJB2, SLC26A4, and mitochondrial m.1555A > G mutations accounted for 18.0%, 13.1%, and 0.9%, respectively." (PMID 24612839, 2014). "Our findings provide a basis for future studies to determine the impact of mutations of the GJB2 and SLC26A4 genes and congenital CMV infection on speech and language outcomes in children with hearing loss." (PMID 23555729, 2013). "In Japanese, GJB2, SLC26A4, CDH23 and the 1555A>G mutation in the mitochondrial 12S rRNA are the major causes of hearing loss." (PMID 24053799, 2013). "Fluctuation and progressiveness of hearing loss are characteristic of hearing loss associated with EVA and the early detection of SLC26A4 mutations enables prediction of these clinical symptoms." (PMID 22384008, 2012). "In this study, we screened the GJB2, GJB3, GJB6, SLC26A4, SLC26A5 IVS2-2A>G and mitochondrial genes to determine the etiology of hearing loss in eastern China." (PMID 23554706, 2011). "SLC26A4 mutations contribute to Pendred syndrome (PS, MIM #274600) or non-syndromic hearing loss (DFNB4, MIM #600791), and some affected patients have progressive or fluctuating hearing loss." (PMID 21811586, 2011). "Ten patients with a family history of hearing loss showed mutations in GJB2, GJB3, GJB6, SLC26A4, mtDNA 12S rRNA, or mtDNA tRNAser(UCN) in our study population." (PMID 19744334, 2009). "Pathogenic variants in SLC26A4 may cause either nonsyndromic recessive hearing loss (DFNB4, OMIM #600791) or Pendred syndrome (OMIM #274600), the latter characterized by hearing loss combined with thyroid dysfunction." (PMID 41226768, 2025). "In our study, we identified a variant of uncertain significance p.P101T in the KCNJ10 gene along with a likely pathogenic variant p.D754Ifs*5 in the SLC26A4 gene and a shortened CEVA haplotype, which involved only three SNPs in a proband with hearing impairment and EVA." (PMID 40426046, 2025). "Pathogenic variants in the SLC26A4 gene (OMIM #605646), leading to non-syndromic recessive hearing loss type 4 (DFNB4) and Pendred syndrome, significantly contribute to the etiology of hearing loss in many populations of the world." (PMID 40144368, 2025). "As a result, the presence of a second, undetected pathogenic variant in the SLC26A4 gene - or in other genes associated with hearing loss - cannot be ruled out in M1 probands." (PMID 40426046, 2025). "Consistent with this, SLC26A4 was identified as the most prevalent deafness-causing gene, accounting for approximately 20% of prelingual-onset NSHL cases, followed by GJB2, in a cohort of Korean patients with hearing loss." (PMID 39609929, 2024). "The CDH23 gene, known for its association with hearing loss, harbors over 400 documented mutations that contribute significantly to non-syndromic hearing loss and are crucial for genetic screenings alongside genes like GJB2 and SLC26A4." (PMID 39596651, 2024).
hearing loss (continued). "In our study, we targeted the limited 20 common variants in GJB2, SLC26A4, 12SrRNA and GJB3 by NGS on universal hearing loss genetic screening for newborns in Jiangxi Province, which showed the advantages of cost efficiency, high throughput and easy interpretation." (PMID 36389375, 2022). "Thus, the molecular etiology presented with high heterogeneity with the leading causes to be SLC26A4 and GJB2 genes in the Chinese hearing loss population." (PMID 35982127, 2022). "SLC26A4 and SLC26A5 genes are risk loci for human asthma and hearing loss, respectively." (PMID 35433778, 2022). "Our previous study has reported two novel mutations (c.85G>A and c.853G>A) and one reported mutation (c.2006A>T) in SLC26A4 in children with non-syndromic hearing loss compared to normal controls (data not shown)." (PMID 36072472, 2022). "Particularly intriguing is the hypothesis of a possible dysfunction of SLC26A4 and SLC26A5 mediated by OS in noise‐induced and/or age‐related hearing loss." (PMID 35143116, 2022). "Sequencing of the EPHA2 gene in 40 Japanese patients with hearing loss and monoallelic mutations in the SLC26A4 gene who were negative for the CEVA haplotype led to the identification of two individuals with potentially pathogenic EPHA2 sequence variants." (PMID 34562878, 2021). "Previous studies correlated the genetic features in terms of number of mutated alleles of the SLC26A4 gene to the severity of the associated IEM, to the entity of the hearing impairment, to the tendency to progression over time of the hearing loss and to the expression of thyroid pathology." (PMID 32910226, 2021). "Sequence analysis of SLC26A4 in these 155 students and teachers with hearing impairment identified that 19 patients carryied two confirmed pathogenic mutations’ alleles, and 8 patients carried one mutant allele, that the pathogenic mutation rate was 17.4% (27/155)." (PMID 30842343, 2019). "As shown in the results for the 208 salivary samples collected from the sporadic moderate-to-profound hearing loss patients, GJB2 and SLC26A4 contributed most mutations, of which, 235delC in GJB2 (43/95, 45.3%) and c.919-2A > G in SLC26A4 (33/95, 34.7%) appeared to be the most common mutations." (PMID 28225033, 2017). "Nevertheless, the high rate of bi-allelic mutations in patients with sporadic profound hearing loss implies that sporadic congenital hearing loss is caused in a majority of cases in Korea by SLC26A4 mutations and not by GJB2 mutations." (PMID 28383030, 2017). "The occurrence of Pendred syndrome usually mandates biallelic SLC26A4 mutations, and manifests universally with congenital or postnatal progressive sensorineural hearing loss, whereas thyroid dysfunction is usually mild or absent." (PMID 27525530, 2016). "SLC26A4 and CDH23 mutations were frequently identified in patients with severe to profound hearing loss, whereas KCNQ4 gene mutations and m.3243A>G mutations were frequently identified in patients with hearing loss ranging from mild to moderate." (PMID 27627659, 2016). "Finally, 48.67% of the patients were identified with hereditary hearing loss caused by mutations in GJB2, SLC26A4, and mtDNA12SrRNA." (PMID 27247933, 2016). "Recessive mutations in SLC26A4 are responsible for non-syndromic enlarged vestibular aqueduct (EVA) and Pendred syndrome, which are often associated clinically with progressive or fluctuating hearing loss." (PMID 26397989, 2015). "Mutations of the SLC26A4 gene (OMIM *605646) are the second most frequent cause of autosomal recessive non-syndromic SNHL (Hilgert, Smith & Van Camp, 2009) and produce a phenotypic spectrum of hearing loss disorders encompassing both Pendred syndrome (PDS; OMIM #274600) and DFNB4 (OMIM #600791)." (PMID 24860705, 2014).
hearing loss (continued). "A total of 35.74% deaf patients showed evidence of genetic involvement based on either genetic screening or family history, and 17.45%, 9.79%, and 8.51% of the patients were determined to have inherited hearing impairment caused by GJB2, SLC26A4, and mtDNA 1555A > G mutations." (PMID 24341454, 2013). "Additional findings of double heterozygous mutations associated with hereditary hearing loss have been reported for KCNJ10 and SLC26A4 and for FOXI1 and SLC26A4, and some mutated genes may have a modifying effect." (PMID 24164807, 2013). "In this study, a total of 35.74% deaf patients showed evidence of genetic involvement, based on either genetic screening or family history; 17.45%, 9.79%, and 8.51% of the patients were determined to have inherited hearing impairment caused by GJB2, SLC26A4, and mtDNA 1555A > G mutations." (PMID 24341454, 2013). "A total of 35.74% deaf patients showed evidence of genetic involvement, based on either genetic screening or family history, and 17.45%, 9.79%, and 8.51% of these patients were determined to have inherited hearing impairment caused by GJB2, SLC26A4, and mtDNA 1555A > G mutations." (PMID 24341454, 2013). "SLC26A4 gene mutations were detected in nearly 20% of our nonsyndromic hearing impairment patients, with IVS7-2A>G being the most prevalent mutation." (PMID 19744334, 2009). "Sequence analysis of SLC26A4 in these 111 patients with hearing impairment identified 16 patients (1 to 16) with two confirmed pathogenic mutations, and one (Patient 17) with compound heterozygote of two unclassified variants, Y375C and R470H, which are most likely pathogenic." (PMID 19040761, 2008). "In humans, not all cases of EVA are associated with hearing loss, and the functional significance and disease relevance of SLC26A4 expression in RoC/SpCs and vestibular TCs of the cochlear lateral wall remain unclear." (PMID 39932986, 2025). "We developed a multiplex variant detection method by combining allele-specific PCR with STH-PAS to verify the presence or absence of the two SLC26A4 pathogenic variants, c.1707+5G>A and c.2168A>G, that are the most common among Okinawan patients with hearing loss and EVA." (PMID 35207372, 2022). "In our study, we found that wild-type SLC26A4 significantly activated, while SLC26A4 mutants inhibited the PI3K/Akt/mTOR pathway in HEK-293T cells, suggesting that this pathway may be another important mechanism of SLC26A4 mutants in hearing loss." (PMID 36072472, 2022). "However, the possible molecular mechanism of SLC26A4 mutation in hearing loss has not yet been fully elucidated." (PMID 36072472, 2022). "Even if a recent study reported that subjects with biallelic mutation of SLC26A4 showed earlier onset of hearing loss and faster progression, we could not find the same in our cohort." (PMID 32910226, 2021). "Although mutation analysis of SLC26A4 have been applied for diagonsis of PDS and non-syndromic hearing loss, SLC26A4 mutations cannot be detected in approximately one-third of patients with enlarged vestibular aqueduct (EVA), whereas only one mutant SLC26A4 allele was identified in another third." (PMID 30842343, 2019). "It is possible that some of the cases presented here could be ‘co-incidental’ carriers for mutations in SLC26A4 which do not contribute to their phenotype of hearing loss, or that we could have missed single or multiple exon deletions." (PMID 23965030, 2013). "For subjects with SLC26A4-mutation-associated Pendred syndrome or non-syndromic DFNB4, attacks of acute sensorineural hearing loss could be prevented by avoiding head trauma or abrupt barometric pressure changes, thus halting the progression or fluctuation of hearing impairment." (PMID 21811586, 2011).